CXCL10 (C-X-C motif chemokine ligand 10)
Diseases named in the same sentence as CXCL10 in open-access papers (continued):
Sharing a sentence is not in itself a finding about the gene and the disease.
viral infection (continued). "Therefore, we aimed to evaluate whether poly I:C (an experimental model of viral infections) and IL-15 induce CXCL10 production in mucosal tissue." (PMID 24586509, 2014). "While the expression of CXCL9 and CXCL10 has been used as a surrogate for IFN-I expression, these ligands can be induced during acute and chronic viral infection or recall responses by both type I and II IFNs." (PMID 40062995, 2025). "Activation of the IFN-I response by LGTV and ZIKV infections was also supported by significant increases in the CXCL10 and CXCL11 expression after virus infection." (PMID 40431659, 2025). "The viral infection group exhibited significantly increased mRNA levels of IL-6, TNFα, CXCL-2, CXCL-3, CXCL-8/IL-8, and CXCL-10 compared to the NC group." (PMID 40872743, 2025). "Acute infection with CHIKV was characterized by higher concentrations of IP-10/CXCL10, IFN-α, IL-6, and TNF-α, all of which are well-established markers of viral infection and inflammation." (PMID 41346606, 2025). "The expression of CXCR3 ligands, CXCL9 and CXCL10, is key IFN-induced environmental cues that regulate T cell positioning and function during acute and chronic viral infection, and recall responses." (PMID 40062995, 2025). "CXCR3 and its ligands CXCL9, CXCL10 and CXCL11 are known to regulate leukocyte recruitment during numerous viral infections." (PMID 39803542, 2024). "Overlapping genes between the two viral infections surge to 426, with IFIT1 and CXCL10 highly ranked, suggesting a state of sustained immune activation and highlighting the complexity of host responses as the infection progresses." (PMID 39591472, 2024). "We previously administered Poly I:C before viral infection as a preventive approach in LMP7 KO mice to reduce neutrophilic inflammation and CXCL10 release." (PMID 39339860, 2024). "In viral infections, CXCL9 together with CXCL10 play a fundamental role by attracting activated T cells via CXCR3." (PMID 38664730, 2024). "We found that virus-induced mRNA levels of key proinflammatory cytokines, IL6, IL1B, CCL2, and CXCL10, were decreased in monocytic cell lines, namely THP1 and U937, and in PBMCs treated with Senexin B prior to viral infection." (PMID 37376593, 2023). "For example, Hepatitis C (HCV) virus infection and intrahepatic INF-γ drive increased CXCL10 expression through the sinus endothelium and liver cells." (PMID 37693903, 2023). "In consistent with the in vitro results, intravenous administration of XQ2B (10 mg/kg) significantly impaired the production of IFN-β and CXCL10 upon HSV-1 infection in mice, and thus promoted virus infection in the brain tissues of mice." (PMID 37783727, 2023). "In particular, the chemokine ligand CXCL10 and its receptor CXCR3 were explored in a plethora of RNA and DNA viral infections." (PMID 36366543, 2022). "Both CXCL10 and CCL2 are important chemokines involved in the infiltration of leukocytes into the CNS after virus infection." (PMID 35215199, 2022). "We detected tissue-specific chemokine and cytokine storms in response to viral infection, including well-defined biomarkers in severe SARS-CoV-2 and IAV infections such as CXCL10, IL-6, and IL-10." (PMID 35962146, 2022). "Virus infection induced a robust increase of IL-6, CXCL8, TNF-α, CXCL10, COX-2, and RANTES in mRNA level with a dose-dependent manner." (PMID 34552653, 2021). "In contrast, VM resulted in increased concentrations of C4b-binding protein and C-X-C motif chemokine 10 (CXCL10), where the latter chemokine is elevated in plasma during viral infections." (PMID 33821792, 2021). "CXCL10 was an IFN γ-induced protein with a strong connection to inflammatory and infectious diseases including viral infections." (PMID 34367154, 2021). "For example, soluble TNF-related apoptosis-inducing ligand (TRAIL), IFN-γ-induced protein-10 (IP-10, CXCL10) and CRP were used in combination to distinguish between bacterial and viral infection in children and adults." (PMID 34079538, 2021).
viral infection (continued). "Here, we show that CXCL10, CXCL11 and CCL5 known to be expressed in the CNS during various viral infections including those by encephalitic arboviruses were upregulated by either virus, pointing to the induction of a strong inflammatory response." (PMID 33799906, 2021). "For example, C-X-C motif chemokine ligand 10 (CXCL10) also stimulates multiple types of immune cells and has known roles in neuronal injury related to viral infection and in relevant human disorders such as multiple sclerosis." (PMID 34768809, 2021). "Therefore, elevated levels of CXCL10 may reflect the viral infection of peripheral tissues." (PMID 34638953, 2021). "The absolute counts of eosinophils in blood correlated inversely with the peripheral levels of SCF and molecules involved in cell response to viral infection, such as DDX58 (DExD/H-Box Helicase 58, also known as RIG-I), IFNɣ, and CXCL10." (PMID 34548411, 2021). "Several chemokines were also involved in response to viral infection (CCL4, CCL11, CXCL10), bacterial infection (CCL2, CCL3, CXCL10), as well as to toxic substances insults (CCL3, CCL4)." (PMID 32295518, 2020). "First, Type II alveolar cells will secrete a host of inflammatory cytokines in response to viral infection such as IL-1β, IL-6, TNF-α, CXCL10, and CCL2 that will act to recruit other inflammatory cells to help abate the viral infection." (PMID 32760409, 2020). "IFN-α/β stimulates the activation of hundreds of IFN-stimulated genes (ISGs, e.g., CXCL10, RSAD2, etc.), the first line of defence against viral infection." (PMID 32599823, 2020). "Infected cultures also displayed upregulation of viral infection markers IFN-beta, IFIT3, and CXCL10." (PMID 31875556, 2019). "We extended our analysis to a range of ISGs that have previously been identified as being regulated directly by virus infection in an IFN-independent manner i.e., IFIT1, IFIT2, IFIT3, ISG15, CXCL10, Mx1 and Mx2." (PMID 30871003, 2019). "It has been reported that CXCL10 secreted from β cells activates and attracts autoreactive T cells and macrophages to the islets via CXCR3 after viral infection in human autoimmune type 1 diabetes." (PMID 30705364, 2019). "The current findings also show that the cytokine CXCL10 gene expression is strongly induced in podocytes and to a lesser extent in mesangial cells, which could indicate enhanced migration of immune cells to sites of virus infection that could lead to increased inflammation observed in BKVAN." (PMID 31252545, 2019). "We showed that the inhibition of BCLXL specifically induces apoptosis and impaired production of CCL5 and CXCL10, which are ligands for CCR5 and CXCR3, respectively, during in vitro and in vivo viral infections." (PMID 30261081, 2018). "Taken together, these data demonstrate that the CHPV-induced expression of CXCL10 and CCL5 is triggered at the stage after viral infection." (PMID 30001342, 2018). "Like IFN responses, with low MOI value, also CXCL10, CCL5, and TNF-α responses were higher in H5N1-infected Mɸs with low MOI value than with low MOI values in H3N2 or H7N9 virus infection." (PMID 30065728, 2018). "Thus, CSF measurement of IP-10/CXCL10 levels may be useful in identifying a CNS disease state as suspicious for infection with further stratification of the disease using MDC/CCL22 levels into viral versus non-viral infection subtypes." (PMID 30379898, 2018). "Confirming our initial findings, viral infection of PVG rats increased the expression of Th1 and type I IFN target genes (MX1, ISG15, IRF7, and CXCL10)." (PMID 30150981, 2018). "The levels of either gene expression or cytokine proteins (IL-1α, TNFα, IL-6, CXCL10, CCL5, CCL2, CCL3, CCL4, and CCL5) in RSV-infected PMФ are comparable to the H5N3 virus infection." (PMID 28558796, 2017). "In asthmatics IFN-γ, CXCL10/IP10, CXCL11/ITAC, IL-15 and IL-5 increased in bronchial lining fluid following viral infection (all P < 0.05)." (PMID 28373098, 2017).
viral infection (continued). "Activated endothelium can also secrete proinflammatory cytokines and chemokines such as IL-6, MIG/CXCL9, IP-10/CXCL10, type I and type II IFNs, MCP-1/CCL2, and TNF-α in response to a virus infection." (PMID 26965109, 2016). "RIG-I activates p38MAPK, leading to secretion of C-X-C motif chemokine 10 (CXCL-10) and IL-12 in bone marrow-derived dendritic cells following viral infection." (PMID 25101306, 2014). "CXCL10 levels were significantly elevated in acute infections with median concentration 3507 pg/mL for RSV and 4678 pg/mL for other viral infections compared to healthy children (1303 pg/mL)." (PMID 25013801, 2014). "Following a viral infection, CXCL10/IP-10 is secreted by bronchial epithelial cells, and Th1 cells are recruited via CXCR3 to eliminate the intracellular pathogen." (PMID 24692853, 2014). "In this study, we seek to understand the modulation of an important chemokine-CXCL10 by the combined effects of IFN γ and viral infection." (PMID 25033426, 2014). "Similar to MARC-145 cells, the virus infection resulted in increased expression of IL-1β, IL-8, IL-10, CCL2 and CXCL10 in PAMs." (PMID 23637938, 2013). "Additional important ISGs produced during virus infections are chemokines, including IFN-γ-inducible protein of 10 kDA (IP-10, CXCL10), the transcription factor IRF7, and several cellular pattern recognition receptors (PRRs), such as the TLRs and the RLRs." (PMID 21994567, 2009). "The gene expression of ISG15 and CXCL-10 was induced upon virus infection in both types of cells; however, it was not affected by Iristatin." (PMID 39821815, 2025). "Although the ligands of CXCR3—CXCL9, CXCL10, and CXCL11—are key ISGs, it is unknown how blocking IFNAR during viral infection impacts chemokine expression for preferential formation of TSCM cells." (PMID 40062995, 2025). "Additionally, CXCL10 and CXCL11 were pinpointed, shedding light on the organ tissue equivalent’s innate immune response to viral infections." (PMID 38957806, 2024). "CXCL10, a chemokine involved in immune cell recruitment, and IFN-γ, a pro-inflammatory cytokine, play pivotal roles in orchestrating the body's defense against viral infections." (PMID 37915987, 2023). "To explore the effect of SPJ treatment on cytokine expression, we used real‐time PCR and observed that viral infection led to increased expression of cytokines and chemokines, including IL‐6, IL‐1β, TNF‐α, IL‐10, IFN‐α, IFN‐β, and IFN‐γ, as well as CXCL‐2, CXCL‐10, CCL‐2, CCL‐3, and CCL‐5." (PMID 37544014, 2023). "Together, this suggests a predominant role for the CXCR3:CXCL10 axis for lung-homing upon respiratory viral infection and also in non-viral lung tissue injury." (PMID 35371005, 2022). "When nontreated ID8 and MCA205 cells were compared, higher basal levels of antiviral response genes (e.g., Cxcl10, Ifnb, Il1b) and lower basal levels of dsRNA sensor genes (e.g., Ddx58, Tlr3) were observed in MCA205 cells, which would limit viral infection/replication and detection, respectively." (PMID 34922008, 2022). "SARS-CoV-2 Plpro antagonistic activity against ISG-15 might block the production of various cytokines involved in the activation of the innate immune response against viral infection, e.g., Type I IFN-β and chemokines such as CXCL10 and CCL5." (PMID 35891385, 2022). "Microglia are already known to induce CXCL10 and ISG15 expression during viral infection." (PMID 36680128, 2022). "Other cytokines and chemokines, including CXCL-8 (IL-8), CXCL-10 (IP-10), TGF-β and TNF-α protein, and type I IFN (IFN-β) and type III IFN (IFN-λ1) mRNA were increased to a similar extent during viral infection and co-infections with either of the PA isolates and HRV16." (PMID 35265536, 2022).
viral infection (continued). "Upon Sendai virus (SeV) stimulation in I‐5 cells, we detected transcription of antiviral genes, such as IFNB, CXCL10, and ISG54, which is comparable to those in wild‐type HEK293T cells, suggesting that I‐5 cells respond normally to virus infection by activation of RIG‐I pathway." (PMID 36216581, 2022). "Whereas the downregulation of lncRNA PVT1 seems to protect pancreatic β cells from injury, both up-regulated MALAT1 and NEAT1 had been related to inflammatory mediators (TNF-alpha, IL-6, CXCL10), SLE pathogenesis and innate immune response against viral infections." (PMID 35058920, 2021). "Upregulated expression of cytokines, chemokines and growth factors was commonly observed in patients and animals with lymphopenia induced by viral infection, including IL-2, IL-6, IL-12, IL-18, IL-1β, IFN-γ, CCL2/MCP-1, CXCL1, CXCL8/IL-8, CCL3/MIP-1-α, CCL7/MCP-3, CXCL10/IP-10 and CXCL9/MIG." (PMID 34578457, 2021). "Viral infections lead to inflammation of the lungs, via recruitment and production of neutrophils, eosinophils, CD4+ cells, CD8+ cells, and mast cells through increased expression and secretion of IL-6, IL-8, CXCL10/IP-10, CCL5/RANTES, and other cytokines." (PMID 34666750, 2021). "The comparable transcript levels of CXCL10, CCL2, and BCL2, as well as viral loads were observed between control and rIL-22-treated groups, indicating that IL-22 was dispensable for the growth, activation, and viral infection of human glial cells." (PMID 32843067, 2020). "Meanwhile, we found that IFNs could significantly trigger the production of a variety of IFN-induced genes (IFIT1, IFITM3, Mx-1, OASL, ISG15, PKR, GBP1, Viperin, BST2, IRF-1, and CXCL10) and MHC molecules, which play key roles in resistance to virus infection." (PMID 32655518, 2020). "IL-21 causes autoantibody production, which downregulates regulatory T cells leading to enhanced autoimmunity and increased CD8+ T cells and NK cells in AE, whereas IP10/CXCL10 is secreted in response to IFN-γ, which is produced as part of the Th1 in response to viral infection." (PMID 33396564, 2020). "Resting microglia do not express CXCL10, but the expression is induced in microglia activated by viral infection of the brain." (PMID 32265633, 2020). "In acutely infected IAV patients, serum/plasma levels of IL-6, IL-8, IL-15, and CXCL10 (IP-10) are elevated, and airway epithelial cells and alveolar macrophages release CXCL10 and IL-15 in the lung upon stimulation with IFN-γ, viral infection, or other pulmonary diseases." (PMID 31156653, 2019). "In our longitudinal study, we found that, in the absence of viral infection, CXCL10, IL-4, IL-13, CCL4, CCL5, CCL20 and CCL24 were each negatively associated with FVC." (PMID 30463560, 2018). "Moreover, montelukast inhibits eosinophil adhesion induced by CXCL10 and ICAM-1 in vitro, both are virus-infection-related proteins." (PMID 30323811, 2018). "For example, in the absence of viral infection, CXCL10 mRNA, MDA5 mRNA, CXCL10, IL-4, IL-13, CCL4, CCL5, CCL20 and CCL24 were negatively associated with FVC." (PMID 30463560, 2018). "When viral infection occurs, viral recognition receptors, such as Toll-like receptor 3 (TLR3) expressed on BECs, are activated to produce inflammatory cytokines and chemokines, including CXCL10." (PMID 28775743, 2017). "The results presented here demonstrate that the chemokines CXCL9 and CXCL10 were produced in response to viral infection of microglial cells, but not in response to viral infection of primary astrocytes." (PMID 27207308, 2016). "The addition of SAPS liposomes at various times following viral infection suppressed the release of the proinflammatory cytokines, CXCL8 and CXCL10, as well as the interferon-stimulated gene CCL5/RANTES from epithelial cell lines and normal and diseased primary human bronchial epithelial cells." (PMID 26906404, 2016). "However, these increases in ISG54 and CXCL10 mRNA levels were much lower for IE1(Δ290–320) and IE1(Δ421–475) virus infections." (PMID 25812002, 2015).
viral infection (continued). "Previous studies have shown that the CXCL10 and its receptor CXCR3 play a vital role in the inflammatory response by attracting activated T lymphocytes to the CNS following viral infections such as Lymphocytic Choriomeningitis virus, Japanese encephalitis virus, and West Nile virus." (PMID 23693026, 2013). "CXCL10 is highly induced in avian flu (H5N1)-infected ferrets, non-human primates, and human cells including alveolar epithelial cells and monocyte-derived macrophages, and has been viewed as a prognostic marker for several viral infections." (PMID 22396727, 2012). "Elevated CXCL10 is also detected in other chronic viral infections, including HCV, and HCV/HIV coinfection, suggesting a role in the immune response to viral infections." (PMID 22363505, 2012). "Our results demonstrate that genes related to important immune pathways such as antigen presentation, inflammation, apoptosis and response to virus (Cxcl10, CxCl11, Ccl5, Ifr7, Ifi27 Oas1b, Fcerg1,Mif, Clusterin and MHC class II) were upregulated as a result of virus infection." (PMID 18558011, 2008). "Here, we will review some of our studies that focused on dissecting the precise mechanism of how TNFα, interferon-inducible protein of 10kDa (IP-10, CXCL10) or general virus infections can induce, accelerate or abrogate autoimmune disease in an animal model for T1D." (PMID 23675028, 2007). "CXCL-9 and CXCL-10 are STAT1-dependent inflammatory factors induced by different cell populations in response to interferons and IL-27, and their expression correlates with the induction of interferon-stimulated genes (ISGs) which promote an antiviral state to control viral infections." (PMID 40711072, 2025). "Importantly, at the cutoffs described in this paper, a negative CXCL10 test would be useful for ruling out viral infection but a positive CXCL10 test would not rule in viral infection." (PMID 40543450, 2025). "In contrast, newborns had a transcriptional signature dominated by the downregulation of genes involved in mitotic, cell cycle, and activation processes; the near absence of a viral infection response; and upregulation of CXCL10, a biomarker of greater disease severity." (PMID 39190496, 2024). "However, CXCL10 expression is not always specific to viral infection, as evidenced by the S+/V- samples that also had higher CXCL10 expression than S-/V- samples, despite testing negative for viruses by multiplex PCR panel and metagenomic sequencing." (PMID 38756971, 2024). "Inflammatory gene sets, and individual inflammatory maker genes CXCL10, CXCL11 and CCL5, were significantly increased in the buffer-only treated cultures from 24 hours to 48 hours, in a viral dose-dependent manner, indicating that the virus infection drives this expression over time." (PMID 39621805, 2024). "Our results indicate that IEC might selectively regulate CCL20, CXCL10 and CCL5 in order to restrict the propagation of the viral infection and the subsequent tissue damage, thus promoting local clearance of the virus and facilitating re-establishment of tissue homeostasis." (PMID 36142892, 2022). "However, in some cases, like viral infection, neurons expressing CXCL10 trigger inflammatory responses in the absence of glial cells." (PMID 36483597, 2022). "Finally, recent studies suggest that serum IP-10 level may be an important biomarker for various viral infections and CXCL-10/IP-10, among other chemokines, is also related with mortality rate." (PMID 34040002, 2021). "Primary SARS-CoV-2 respiratory infection induces systemic inflammation (CXCL10, IFN-ɤ, IL-1B, IL-6, IL-8, IL-17, TNF-α) that can impact the musculoskeletal system through the expression of hACE2-R and TMPRSS2 genes in various types of musculoskeletal cells, allowing direct viral infection." (PMID 33919537, 2021).